TLR8 (toll like receptor 8)
Diseases named in the same sentence as TLR8 in open-access papers (continued):
Sharing a sentence is not in itself a finding about the gene and the disease.
infection (continued). "Although WT infection-specific regulation was observed only for TLR8 and IFNGR1, all four genes were expressed at higher levels (TLR8 and TLR9) or at lower levels (IFNGR1 and PYCARD) in the WT-infected dTHP1 cells than in the mock-treated or ΔrtxA1 mutant-infected dTHP-1 cells." (PMID 32817457, 2020). "PrimePCR array analysis of hNS/PCs showed that the mRNA levels of inflammatory cytokine related genes (IL-1A, TNFα, IL28A, IL29, NF-KB2), chemokines (CSF2, CCL3, CCL4, CXCR3),TLRs (TLR3, TLR8), IL-10, and Casp9 were all reduced in the Smaducin-6 treated group following ZIKV-FSS13025 infection." (PMID 32544190, 2020). "The variant was a cis-eQTL for IFNB1 after activation of the TLR1/TLR2, TLR4, and TLR7/TLR8 pathways, but not after infection with an influenza virus." (PMID 33147208, 2020). "Taken together, we hypothesize that bacterial sensing via TLR8 and TLR2, in combination with IL-1R- and NOD/NLR-signaling, is critical in the defense against pyogenic infections in infants and children." (PMID 31214180, 2019). "The impact of TLR8 during infection is unclear because neither small animal models nor selective and efficient inhibitors have been available." (PMID 31214180, 2019). "With ECO 17-1 infection there was a tendency for increased levels of nuclear IRF5, which might reflect a low TLR8-agonistic activity of this isolate." (PMID 31214180, 2019). "As such, TLR2, TLR3, TLR4, TLR7, TLR8, and TLR9 are known to recognize EBV during infection." (PMID 31238570, 2019). "Still, we do not know how important TLR8 is in the skin and the airway mucosa, the sites where these infections typically arise." (PMID 31214180, 2019). "TLR8 inhibition also strongly reduced TNF and IL-6 induction by GBS and S. aureus, and reduced IL-10 production at the late time point, while TLR8-inhibition increased the level of IL-8 after 22 h of infection with the highest dose of bacteria." (PMID 31214180, 2019). "However, in placenta cells, we saw that siRNA against TLR8 significantly decreased AXL expression after three days, with a similar downregulation also observed after TLR7 knockdown three days after infection." (PMID 30453684, 2018). "Collectively, these results demonstrate that the induction of autophagy in macrophages by HIV does not require productive infection, and is mediated through a TLR8 signaling pathway that requires endosomal maturation." (PMID 26115100, 2015). "Irrespective of their biological role during infections, the network of innate immune cells able to respond to TLR8 agonist within the liver sinusoids can open new therapeutic opportunities." (PMID 24967632, 2014). "Similarly, Grighuis and co-workers have recently demonstrated that HIV-1 exploits TLR8- and DC-SIGN-mediated signalling cascades to achieve productive infection of DCs." (PMID 23844079, 2013). "Recognition of released HIV-1 genomic RNA by TLR8 and binding of HIV-1 envelope protein to DC-SIGN provide two signals that are essential for initiation of transcription and production of full length viral transcripts, thus also enhancing infection in cis." (PMID 22163292, 2011). "HIV and SIV clearly affect mDC in the absence of productive infection, in particular through interactions of viral RNA with endosomal TLR8; however this interaction tends to promote cell survival rather than apoptosis." (PMID 21203477, 2010). "Interestingly, despite their enhanced responsiveness to the viral RNA, TLR7- and TLR8-overexpressing cells did not react to the infection with replication-competent SARS-CoV-2, since we measured only negligible eGFP expression by flow cytometry." (PMID 39963132, 2025). "Furthermore, we evaluate the impact of the timing of ART initiation on TLR8 and RLR crosstalk in PWH by investigating these responses at different stages of infection; CHI, and AHI at 24 and 156 weeks after treatment initiation (AHI-24 and -156) as compared to HIV uninfected individuals." (PMID 41206241, 2025).
infection (continued). "IL-18 production by monocytes exposed to HIV-1 was dependent on endocytosis rather than infection, and both studies found that TLR-8 activation was required for induction of pro-IL-1β whereas cleavage into its active form and release was dependent upon NLRP3 and the inflammasome adaptor protein ASC." (PMID 29056936, 2017). "However, the molecular components required for TLR8 signaling in DCs and how HIV‐1 might manipulate that to avoid interferon responses while enhancing trans‐infection are unclear." (PMID 28923824, 2017). "Despite the downregulation of autophagy markers observed by 7 d post-infection, CYP27B1 and VDR were still significantly upregulated indicating that TLR8 is still sufficiently engaged at these late time posts post-infection in the absence of significant cytotoxic effects (P > 0.05)." (PMID 26115100, 2015). "Collectively, these data suggest that exposure of macrophages to HIV induces TLR8-dependent TFEB dephosphorylation and nuclear translocation that induces autophagy, and that this is not dependent upon a productive infection." (PMID 26115100, 2015).
cancer (67 papers, 2012 to 2026). A tumor composed of atypical neoplastic, often pleomorphic cells that invade other tissues. "Transcriptional activation of a HERV-H provirus integrated downstream of the tandem TLR7 and TLR8 loci on human chromosome X initiates antisense transcription that is associated with loss of TLR7 and TLR8 transcription in several cancer types." (PMID 40773553, 2025). "Single-stranded RNA has inherent adjuvant function stimulated by TLR7 and TLR8, and its relative ease in encoding multiple vaccine epitopes on the same RNA molecule indicates its advantages as a cancer vaccine formulation." (PMID 39136021, 2024). "They suggested that genetic TLR polymorphisms, especially in X-chromosome-linked TLR8, affect the innate immune response and make certain populations and individuals more vulnerable to infection-related cancers." (PMID 31238894, 2019). "In the context of cancer, TLR8 is implicated in the activation of antitumor immune responses." (PMID 41208992, 2025). "Recent studies have indicated an essential, yet dual role for TLR7 and TLR8 also in cancer progression and immune control." (PMID 40336011, 2025). "The wide range of expression and clinical significance of TLR7/TLR8 in different kinds of cancers have been extensively explored." (PMID 36476317, 2022). "Many studies have revealed that the expression levels of TLR7 and TLR8 are altered in some autoimmune diseases, such as arthritis, cancers, or in antiviral regimes, including corona virus prevention and HIV." (PMID 35452465, 2022). "miRNAs play direct or indirect roles in regulating oncogenes (KRAS), tumor suppressor genes (FHIT, WWOX), and immune-related gene (TLR8), which ultimately promote cancer cell growth and dissemination." (PMID 34470640, 2021). "The Toll-like receptor 8 (TLR8) agonist VTX-2337 (motolimod) is an anti-cancer immunotherapeutic agent that is believed to augment natural killer (NK) and dendritic cell (DC) activity." (PMID 33452311, 2021). "Many of the deregulated genes seem to be directly connected to GWAS or cancer driver genes such as TLR8, CASP1, and TNFRSF10B." (PMID 33717131, 2021). "In view of the potential application of Vδ2 T cells as effector cells in cell-based cancer immunotherapy, we investigated the modulation of the activation and proliferative Vδ2 expansion by TLR8 and TLR7/8 ligands." (PMID 32183240, 2020). "The results show that TLR8 gene expression level decreased significantly in Ramos cancer cell line in the presence of silymarin (100μg/ml) in comparison to untreated cells (p<0.01)." (PMID 32257888, 2020). "The current study focused on the effect of silymarin on TLR8 expression inhibition, cell viability, and induction of apoptosis in Ramos cancer cell line." (PMID 32257888, 2020). "TLR8 mRNAs in cancer cell line was detected, and also the effects of silymarin on expression of the TLR8 gene was performed at different times (o[control], 4, 8, 12, 24 and 48 hr)." (PMID 32257888, 2020). "The expression levels of TLR8 were examined by real-time RT-PCR using SYBR Green in Ramos cancer cells." (PMID 32257888, 2020). "The current study aimed at examining the effect of silymarin on TLR8 gene expression and induction of apoptosis in Ramos cancer cell line." (PMID 32257888, 2020). "Since motolimod is a closely related TLR8 agonist in clinical development for cancer indications we included motolimod as a reference benchmark molecule in our study." (PMID 35006413, 2020). "In summary, the current study data indicated downregulation of TLR8 expression after silymarin treatment in Ramos cancer cells." (PMID 32257888, 2020). "In this study we focused on TLR7 and TLR8, as ligands for these two receptors are in clinical use or development for cancer therapy." (PMID 32183240, 2020).
cancer (continued). "The results of the current study showed a significant positive correlation between Ramos cancer cell line with silymarin and reduced expression of TLR8 and apoptosis in a concentration- and time-dependent fashion; silymarin also increased caspase-3 activity." (PMID 32257888, 2020). "Agonists of TLR7 and TLR8 including imidazoquinolines are currently being used or tested in clinical trials as anti‐viral and anti‐cancer drugs." (PMID 28923824, 2017). "VTX-2337 is a potent TLR8 agonist that is currently in Phase 2 clinical development as an immunotherapy for multiple cancer indications, including SCCHN." (PMID 26928328, 2016). "We are conducting a clinical trial to determine if patients with advanced cancers tolerate and respond to combinational treatment with CY and the novel TLR8 agonist motolimod as meaningfully as mice treated with CY+CpG ODN 1826." (PMID 27341020, 2016). "The release of IL-18 and other TLR8-induced mediators augment NK cell activation signals in cancer patients." (PMID 26928328, 2016). "The promoting effect of TLR7 and TLR8 expression on PANC1 cancer cell proliferation was analyzed using MTS proliferation assays." (PMID 26134824, 2015). "Seventy-two hours after stimulation with R848 NF-κB expression returned to background levels in both TLR7+ and TLR8+ PANC1 cancer cells." (PMID 26134824, 2015). "Gene expression of the proliferation marker Ki-67 in R848 treated TLR7+ and TLR8+ PANC1 cancer cells confirmed these proliferative effects." (PMID 26134824, 2015). "Altogether, these data and ours highlight, on the contrary, the interest of using TLR8 synthetic agonist in vitro in cancer adoptive cell therapy." (PMID 25866635, 2015). "For both concentrations increased cell viability of TLR7+ and TLR8+ PANC1 cancer cells was demonstrated when compared to empty vector PANC1 cells, pointing to an increased chemoresistance in the cells." (PMID 26134824, 2015). "Even 72 h post-stimulation COX-2 expression levels remained significantly elevated in stimulated TLR7+ and TLR8+ cancer cells in comparison to untreated cancer cells." (PMID 26134824, 2015). "Stimulation with R848 for 6 h induced an ~4-fold increase in gene expression levels of NF-κB in TLR7+ and TLR8+ PANC1 cancer cells compared with untreated cells (P<0.0001)." (PMID 26134824, 2015). "There were strong TLR1 and TLR8 immunoreactivities in the cancer cells and in some inflammatory cells in the mucosa." (PMID 25547486, 2014). "Exosome-contained miRNAs (namely, miR-21 and miR-29a) can be engulfed by the immune cells surrounding cancer cells and they can bind to Toll-like Receptor 8 (TLR8) present in the immune cells." (PMID 25356314, 2014). "TLR7/TLR8 agonists are less developed as adjuvants but are already used with success in topical cancer immunotherapy." (PMID 26344622, 2014). "Notably, HERVH Xp22.2-AS transcription was strongly anti-correlated with TLR7 and TLR8 transcription in cancers where it was expressed." (PMID 40336011, 2025). "Targeting immune system proteins called TLR7 and TLR8 is showing promise in cancer treatment." (PMID 41228373, 2025). "One example of this is R848, a dual TLR7 and TLR8 synthetic agonist previously shown to promote an anti-cancer and anti-bacterial immune response, suggesting that it might also have relevance in wound healing settings as well." (PMID 39078119, 2024). "TLR8 agonist, new cancer immunotherapy, is expected to become potent anti-cancer agents in males." (PMID 36273184, 2022). "TLR7 and TLR8 are key members of the Toll-like receptor family, playing crucial roles in the signaling pathways of innate immunity, and thus become attractive therapeutic targets of many diseases including infections and cancer." (PMID 35452465, 2022). "The expression of TLR7 and TLR8 in different kinds of cancers has been studied." (PMID 36476317, 2022).
cancer (continued). "Studies have found different metabolism ways of regulatory T cells (Tregs) in the cancer environment may be related to the immunosuppression and Toll-like receptor 8 (TLR8) can reverse the suppression function of Tregs." (PMID 33414414, 2021). "Therefore, reversing Treg and MDSC mediated immune suppression by activating TLR8 can elicit potent immune response resulting in strong anti-cancer effect." (PMID 35006413, 2020). "Notably, stimulation of TLR7 and TLR8 in the present study also resulted in a more robust chemoresistance in PANC1 cancer cells against 5-fluorouracil." (PMID 26134824, 2015). "Moreover, TLR7 and TLR8 stimulation in human PANC1 cancer cells led to the release of inflammatory mediators, mainly through the activation of the NF-κB pathway." (PMID 26134824, 2015). "We examined whether TLR7 and TLR8 stimulation with the agonist R848 further increases proliferation of TLR7+ and TLR8+ PANC1 cancer cells." (PMID 26134824, 2015). "We investigated the results that suggest that induction of TLR8 by 3M002 in CRC cancer cell lines can reduce the secretion of IL-6 and IL-8, however, the cellular mechanisms associated with the inhibition of metastasis particularly driven by 3M002 remain to be elucidated." (PMID 25547486, 2014). "The results from IFN-α and MyD88 in cancer tissues suggested that the TLR8 signaling pathway may be different in cancer tissues from the antiviral responses in which TLR8 induces antiviral responses by MyD88-dependent-producing IFN-α." (PMID 25547486, 2014). "They found that motolimod treatment reduced MDSCs levels in healthy donors and cancer patients, and concluded that TLR8 agonists could be deployed in conjunction with cancer immunotherapeutic approaches in order to enhance the anti-tumor effects of the adaptive immune response." (PMID 36739406, 2023). "In addition, these investigators reported that cancer cell-derived exosomal miRNAs can bind to and activate TLR8 in macrophages and stimulate TLR8-mediated activation of NF-κB and NF-κB–mediated release of the proinflammatory and prometastatic cytokines IL-6 and TNF-α." (PMID 31139186, 2019). "Additionally, stimulation with R848 induced an ~60-fold increased gene expression of COX-2 in TLR7+ PANC1 cancer cells (12 h after stimulation) and an ~34-fold increased level in TLR8+ PANC1 cells (24 h after stimulation) compared with untreated cells (P<0.005 and 0.0001)." (PMID 26134824, 2015). "Keywords used in the search included: TLR7 agonist, TLR8 agonist, TLR7/8 agonist, TLR7/8-based cancer vaccine, TLR7/8-based cancer immunotherapy, TLR7/8-based combination treatment, and TLR7/8-based clinical trials." (PMID 41228373, 2025). "The results showed that PTPRC, TLR8, PLEK, NCKAP1L, RGS18 and CLEC12A displayed strong correlation with GPR141 in most cancer types." (PMID 40959105, 2025). "Modulation of the immune system has emerged as a key strategy in novel cancer therapies, demonstrating potential across various cancer types, including the recent exploitation ofTLR‐like receptors (TLR7, TLR8) and STING." (PMID 40606778, 2025). "We performed correlation analysis of these six genes (PTPRC, TLR8, PLEK, NCKAP1L, RGS18 and CLEC12A) with GPR141 in pan-cancer." (PMID 40959105, 2025). "Imidazoquinolines (IMDs), such as resiquimod (R848), are of great interest as potential cancer immunotherapies because of their ability to activate Toll-like receptor 7 (TLR7) and/or TLR8 on innate immune cells." (PMID 37075115, 2023). "The immune-based anti-cancer mechanisms of RSQ are similar to those of IMQ; however, RSQ has the advantage of being able to trigger both TLR-7 and TLR-8 signaling." (PMID 36297510, 2022). "Stimulation of TLR7/TLR8 expression resulted in elevated NF-κB and COX-2 expression and, more importantly, increased cancer cell proliferation and reduced chemosensitivity." (PMID 36476317, 2022).